PSMD7 (proteasome 26S subunit, non-ATPase 7)
Description:
Component of the 26S proteasome, a multiprotein complex involved in the ATP-dependent degradation of ubiquitinated proteins. This complex plays a key role in the maintenance of protein homeostasis by removing misfolded or damaged proteins, which could impair cellular functions, and by removing proteins whose functions are no longer required. Therefore, the proteasome participates in numerous cellular processes, including cell cycle progression, apoptosis, or DNA damage repair.
Synonyms: S12; P40; MOV34; Rpn8
Tractability: Small molecule: an approved drug acts on it; a structure with a bound ligand is known; a high-quality ligand is known. Antibody: its Gene Ontology location is reachable by antibodies, with high confidence. PROTAC: UniProt records ubiquitination sites on it; ubiquitination databases record sites on it; its protein half-life has been measured.
Target class: Enzyme
Gene: Protein-coding gene on chromosome 16 (74,296,809 to 74,306,288, forward strand). Ensembl gene ENSG00000103035.
Subcellular location (Human Protein Atlas): Acrosome; Equatorial segment; Mid piece; Nucleoplasm; Principal piece
Pathways (Reactome):
Immune System: AMPK-induced ERAD and lysosome mediated degradation of PD-L1(CD274); Activation of NF-kappaB in B cells; Antigen processing: Ubiquitination & Proteasome degradation; CLEC7A (Dectin-1) signaling; Cross-presentation of soluble exogenous antigens (endosomes); Dectin-1 mediated noncanonical NF-kB signaling; Downstream TCR signaling; ER-Phagosome pathway; FCERI mediated NF-kB activation; GSK3B-mediated proteasomal degradation of PD-L1(CD274); Interleukin-1 signaling; NIK-->noncanonical NF-kB signaling; Neutrophil degranulation; SPOP-mediated proteasomal degradation of PD-L1(CD274); TNFR2 non-canonical NF-kB pathway
Cell Cycle: APC/C:Cdc20 mediated degradation of Securin; APC/C:Cdh1 mediated degradation of Cdc20 and other APC/C:Cdh1 targeted proteins in late mitosis/early G1; Autodegradation of Cdh1 by Cdh1:APC/C; Autodegradation of the E3 ubiquitin ligase COP1; Cdc20:Phospho-APC/C mediated degradation of Cyclin A; FBXL7 down-regulates AURKA during mitotic entry and in early mitosis; G2/M Checkpoints; SCF(Skp2)-mediated degradation of p27/p21; SCF-beta-TrCP mediated degradation of Emi1; Separation of Sister Chromatids; The role of GTSE1 in G2/M progression after G2 checkpoint; Ubiquitin-Mediated Degradation of Phosphorylated Cdc25A; Ubiquitin-dependent degradation of Cyclin D
Signal Transduction: Asymmetric localization of PCP proteins; Degradation of AXIN; Degradation of DVL; Degradation of GLI1 by the proteasome; Degradation of GLI2 by the proteasome; Degradation of beta-catenin by the destruction complex; GLI3 is processed to GLI3R by the proteasome; Hedgehog 'on' state; Hedgehog ligand biogenesis; MAPK6/MAPK4 signaling; Negative regulation of NOTCH4 signaling; Regulation of PTEN stability and activity
and 28 more pathways
Gene Ontology:
Molecular function: protein binding; protein homodimerization activity; metal-dependent deubiquitinase activity; peptidase activity
Biological process: cellular response to type I interferon; proteasomal protein catabolic process; proteasome-mediated ubiquitin-dependent protein catabolic process; regulation of proteasomal protein catabolic process; response to oxidative stress
Cellular component: extracellular exosome; membrane; nucleus; proteasome complex; cytosol; extracellular region; ficolin-1-rich granule lumen; nucleoplasm; proteasome regulatory particle; proteasome regulatory particle, lid subcomplex; secretory granule lumen; synaptic vesicle
Genetic constraint (gnomAD): Loss-of-function variants: 11 observed, 26.93 expected, observed/expected ratio (o/e) 0.41, 90% interval 0.26 to 0.68. The upper end of that interval is the gene's LOEUF score, 0.68, which puts it in group 2 of 6, group 1 being the genes least tolerant of losing a copy. Missense variants: 265 observed, 346.44 expected, observed/expected ratio (o/e) 0.76, 90% interval 0.69 to 0.85. Synonymous variants: 166 observed, 139.42 expected, observed/expected ratio (o/e) 1.19, 90% interval 1.05 to 1.35.
Homologues: Orthologues: chimpanzee PSMD7 (100% identical), pig PSMD7 (99% identical), guinea pig PSMD7 (99% identical), mouse Psmd7 (97% identical), rat Psmd7 (97% identical), tropical clawed frog psmd7 (95% identical), zebrafish psmd7 (94% identical), rabbit PSMD7 (80% identical), Drosophila melanogaster Rpn8 (78% identical), Caenorhabditis elegans rpn-8 (67% identical), macaque PSMD7 (59% identical). Paralogues in human: EIF3F (25% identical), COPS6 (23% identical).
Diseases named in the same sentence as PSMD7 in open-access papers:
PSMD7 is named in the same sentence as 39 diseases in open-access papers, as found by Europe PMC text mining. Sharing a sentence is not in itself a finding about the gene and the disease. The quoted sentences say what the papers report.
breast carcinoma (13 papers, 2020 to 2024). "PSMD7 is associated with cell cycle regulation and disease progression in breast cancer, indicating poor prognosis." (PMID 39469643, 2024). "Our previous study found that PSMD7 regulates cell fate and is associated with disease progression in breast cancer." (PMID 34234864, 2021). "Furthermore, we found that PSMD7 regulates cell fate and is associated with disease progression in breast cancer." (PMID 34234864, 2021). "PSMD7 is found highly expressed in breast cancer and positively associated with poor survival." (PMID 33687056, 2021). "PSMD2 and PSMD7 were shown to regulate breast cancer cell proliferation and cell cycle progression by regulating the proteasomal degradation of p21 and p27." (PMID 37349676, 2023). "The level of PSMD7 was significantly elevated in breast cancer and was closely related to tumor subtype, tumor size, lymph node invasion, and tumor-node-metastasis (TNM) stage." (PMID 37350936, 2023). "PSMD7 mRNA expression was found to be upregulated in breast cancer tissue, and knockdown led to cell cycle arrest and apoptosis by decreasing the expression of cell cycle proteins and increasing the stability of the p21 and p27 cell cycle regulators." (PMID 36498916, 2022). "Consistently, our recent report indicated that PSMD7 regulates cell fate and disease progression in breast cancer." (PMID 34234864, 2021). "PSMD7 promotes cell cycle progression and suppresses cell senescence and apoptosis of breast cancer cells by regulating the stability of p21 and p2719." (PMID 34512150, 2021). "Down-regulated PSMD7 inhibits the expression of key cell cycle-related proteins and promotes the stability of p21 and p27 in breast cancer cells." (PMID 33687056, 2021). "Therefore, TRIM21 and PSMD7 play significant roles in the antitumor effect of HTR1A through the TGF‐β pathway in breast cancer cells." (PMID 35199941, 2022). "PSMD7, a core component of the 26S proteasome, may play a role in the progression of breast cancer and could also serve as a prognostic indicator or therapeutic target." (PMID 36498916, 2022). "We analyzed a prognostic model based on seven DDR genes, PSMD2, PSMD7, PSMD14, PARP3, MDC1, PSMB1, and PSMB9, reflecting an enhanced level of predicting the survival and prognosis of patients with breast cancer." (PMID 37350936, 2023). "The protein levels of MDC1, PSMB1, PSMB9, PSMD2, PSMD7, and PSMD14 were increased, while that of PARP3 was decreased in breast cancer tissues compared with normal tissues." (PMID 37350936, 2023). "PSMD7 was considered an oncogene in prostate cancer, esophageal squamous cell carcinoma (ESCC), and breast cancer." (PMID 37349676, 2023). "Our results suggest that focusing on PARP3, PSMB1, PSMD7, and PSMD14 and their roles in immunotherapy is a reasonable strategy for breast cancer treatment." (PMID 37350936, 2023). "The levels of PSMD1, PSMD2, PSMD3, PSMD7, PSMD10, PSMD12, and PSMD14 are high in breast cancer tissue compared to normal tissues." (PMID 36934426, 2023). "Subsequently, we explored the protein levels of MDC1, PARP3, PSMB1, PSMB9, PSMD2, PSMD7, and PSMD14 in normal breast tissues and breast cancer tissues." (PMID 37350936, 2023). "Consistent with the Immunohistochemistry (IHC) results, the expression of MDC1, PSMB1, PSMD2, PSMD7 and PSMD14 were significant augmented in breast cancer patients (P < 0.05)." (PMID 37350936, 2023). "Furthermore, we investigated the function of the five highly expressed genes (MDC1, PSMB1, PSMD2, PSMD7, and PSMD14) in breast cancer MDA-MB-231 cells to test the prognostic model." (PMID 37350936, 2023). "In addition, we investigated the roles of MDC1, PSMB1, PSMD2, PSMD7, and PSMD14 in the invasion and metastasis of breast cancer." (PMID 37350936, 2023).
breast carcinoma (continued). "We established a seven-gene prognostic model comprising MDC1, PARP3, PSMB1, PSMB9, PSMD2, PSMD7, and PSMD14 genes, which provides a basis for further exploration of a population-based prediction of prognosis and immunotherapy response in patients with breast cancer." (PMID 37350936, 2023).
esophageal squamous cell carcinoma (7 papers, 2018 to 2024). Esophageal squamous cell carcinoma (ESCC) is a type of esophageal carcinoma (EC) that can affect any part of the esophagus, but is usually located in the upper or middle third. "A previous study 22 demonstrated that downregulation of PSMD7 led to decreased cell proliferation and increased apoptosis in esophageal squamous cell carcinoma." (PMID 34234864, 2021). "A previous study focused on esophageal squamous cell carcinoma has reported that downregulating PSMD7 expression level could effectively elicit the apoptosis and suppress the proliferation of the cancer cells." (PMID 35037550, 2022). "It has been shown that in esophageal squamous cell carcinoma (ESCC), downregulated PSMD7 induces apoptosis and inhibits the aggressive behaviors of ESCC cells through the mTOR/p70S6K pathway." (PMID 35037550, 2022). "Knockdown of PSMD7 inhibits tumorigenesis and induces cell apoptosis in esophageal squamous cell carcinoma (ESCC) via the mTOR/p70S6K pathway." (PMID 33687056, 2021). "Recent studies have revealed the role of PSMD7 in prostate cancer, esophageal squamous cell carcinoma (ESCC), and breast cancer." (PMID 34512150, 2021). "In this study, we explored the role of PSMD7 in proliferation, cell cycle, apoptosis, and proteasomal proteolysis in the esophageal squamous cell carcinoma (ESCC) cell line EC9706." (PMID 29632807, 2018).
gastric cancer (6 papers, 2021 to 2024). A primary or metastatic malignant neoplasm involving the stomach. "Finally, the special mechanisms underlying the cellular effects of PSMD7 knockdown on gastric cancer cells are still unclear, which will be our focus in further study." (PMID 35037550, 2022). "Additionally, silencing PSMD7 in gastric cancer cell line HGC-27 was shown to be able to induce the loss of cell viability and proliferative capacity and speed up cell apoptosis." (PMID 35037550, 2022). "Previous research has reported that the overexpression of the deubiquitinase PSMD7 promotes gastric cancer cell proliferation, invasion, and cisplatin resistance by stabilizing RAD23B." (PMID 39469643, 2024). "In this study, we explored the biological role of PSMD7 and the potential mechanism in gastric cancer cells." (PMID 35037550, 2022). "PSMD7 is involved in the proliferation and apoptosis of gastric cancer cells and can be transcriptionally regulated by FOXP3." (PMID 35037550, 2022). "In this study, we aimed to explore the role of PSMD7 in gastric cancer cells and the combination between PSMD7 and FOXP3." (PMID 35037550, 2022). "The data revealed that the expression of PSMD7 was significantly increased in gastric cancer tissues and cell lines." (PMID 35037550, 2022). "Firstly, we explore the role of FOXP3-mediated PSMD7 in proliferation and apoptosis in gastric cancer cells, but more functional experiments should be assessed to widely investigate the role of PSMD7 in gastric cancer." (PMID 35037550, 2022). "PSMD7 expression was much higher in gastric cancer tissue and cell lines." (PMID 35037550, 2022). "The present determined PSMD7 upregulation in both gastric cancer tissues and cell lines." (PMID 35037550, 2022). "It is worth noting that PSMD7 is required for general cell survival, and whether the reduced cell viability is specific to gastric cancer cells is still unclear." (PMID 35037550, 2022). "The silencing of PSMD7 inhibits proliferation and induces apoptosis in gastric cancer cells." (PMID 35037550, 2022). "Thus, PSMD7 silencing reversed FOXP3 overexpression-inhibited gastric cancer cell apoptosis." (PMID 35037550, 2022). "Thus, PSMD7 silencing expedited the apoptosis of HGC-27 gastric cancer cells." (PMID 35037550, 2022). "PSMD7 is particularly important in maintaining chemoresistance, as seen in its role in stabilizing RAD23B in gastric cancer, contributing to resistance against cisplatin treatment." (PMID 39469643, 2024). "Therefore, PSMD7 promoting gastric cancer tumorigenesis could be a reasonable conjecture." (PMID 35037550, 2022). "PSMD7 and FOXP3 have the potential to be meaningful biological indicators of gastric cancer and may be applied to the development of novel agents or targeted therapy as candidate molecular targets." (PMID 35037550, 2022). "We hypothesized that the transcriptional activation of PSMD7 by FOXP3 may inhibit cell proliferation and facilitate cell apoptosis in gastric cancer." (PMID 35037550, 2022). "PSMD7 expression in non-cancerous gastric tissue or cells and gastric cancer tissue or cells was detected by qPCR and Western blot." (PMID 35037550, 2022). "In order to understand the mechanism responsible for the function of PSMD7 in gastric cancer cell proliferation and apoptosis, bioinformatic tools including PROMO and JASPAR databases were searched for potential interaction between PSMD7 and putative transcription factors." (PMID 35037550, 2022). "Additionally, the putative targets of miR-497-5p including PSMD7, CCND3, SMURF2, and WNT7A increase chemoresistance in gastric cancer, acute myeloid leukemia, lung cancer and OSCC, respectively." (PMID 36703917, 2022). "We used RT-qPCR and Western blot assay to quantify the PSMD7 expression in gastric cancer tissues, but we did not explore the expression pattern of PSMD7." (PMID 35037550, 2022). "Proteasome 26S Subunit, Non-ATPase 7 (PSMD7) is highly expressed in gastric cancer." (PMID 39115875, 2024).
gastric cancer (continued). "Moreover, PSMD7 can enhance the deubitization of RAD23 homolog B (RAD23B) protein, reduce the degradation of RAD23B, and promote the proliferation, invasion and cisplatin resistance of gastric cancer cells." (PMID 38494478, 2024). "Proteasome 26S non-ATPase subunit 7 (PSMD7) and forkhead box P3 (FOXP3) have been found to be both upregulated in gastric cancer tissues." (PMID 35037550, 2022).
lung carcinoma (5 papers, 2021 to 2024). "Recent reports have revealed that PSMD7 aberrant expression in breast and lung cancer tissues is associated with poor prognosis." (PMID 38494478, 2024). "In summary, our results show that the PSMD7 level is increased in lung cancer tissues and is closely related to clinical features." (PMID 34234864, 2021). "Currently, PSMD7 expression and its roles in the progression of lung cancer remain largely unknown." (PMID 34234864, 2021).
lung adenocarcinoma (4 papers, 2020 to 2023). A carcinoma that arises from the lung and is characterized by the presence of malignant glandular epithelial cells. "PSMD7 expression was also closely associated with lymph node invasion and the laterality of the tumor in lung adenocarcinoma (LUAD)." (PMID 34234864, 2021). "Highly expressed PSMD2 and SMD14 were greatly related to lymph node metastases and TNM phase of lung adenocarcinoma, while high expression of PSMD2, PSMD7, PSMD14 were linked to poor OS and/ or disease-free survival (DFS) among these patients." (PMID 37337223, 2023). "Another study has also observed accelerated apoptosis and inhibited tumor growth of lung adenocarcinoma after the knockdown of PSMD7 in vitro and in vivo." (PMID 35037550, 2022).
pancreatic cancer (4 papers, 2020 to 2025). "Through GEO2R analysis of the GSE118916 chip expression data from the National Center for Biotechnology Information (NCBI), it was found that PSMD7 is highly expressed in pancreatic cancer tissues." (PMID 35037550, 2022). "Additionally, the co-localization of SOX2 and PSMD7 in pancreatic cancer cells was confirmed by confocal microscopy, providing further substantiation for the protein-protein interaction." (PMID 38494478, 2024). "However, the clinical significance and biological functions of PSMD7 in pancreatic cancer (PC) remain unclear." (PMID 38494478, 2024).
bladder cancer (2 papers, 2020 to 2025). "In bladder cancer, the deubiquitinating enzyme PSMD7 promotes tumor development by stabilizing RAB1A expression." (PMID 40413536, 2025).
ankylosing spondylitis (1 paper, 2023). An autoimmune chronic inflammatory disorder characterized by inflammation in the vertebral joints of the spine and sacroiliac joints. "A polymorphism (rs17336700) in the PSMD7 gene is associated with ankylosing spondylitis in Chinese subjects." (PMID 36658473, 2023).
breast tumor (1 paper, 2021). "Immunohistochemical (IHC) images revealed dense distributions of PSMD2 and PSMD4, while the other PSMDs, including PSMD1, PSMD2, PSMD3, PSMD7, PSMD12, and PSMD14, were moderately distributed in breast tumor samples." (PMID 34839279, 2021).
diabetes (1 paper, 2020). "In the group enriched with diabetic patients (6 out of 9 patients), seven proteasome genes (PSME4, PSMA7, PSMB4, PSMB6, PSMC4, PSMD7 and PSMD8) and three genes previously associated with common diabetes (SNX17, PARK7/DJ-1 and ATP5B) were highly expressed." (PMID 32302349, 2020).
sarcoma (1 paper, 2024). A usually aggressive malignant neoplasm of the soft tissue or bone. "In cellular experiments, we observed significantly upregulated mRNA expression of CALR, CASP3, BCL10, PSMD7, and PSMD10 in sarcoma cell lines compared to their corresponding normal cell lines." (PMID 39469643, 2024).
spinocerebellar ataxia (1 paper, 2025). "Among the most significantly enriched proteins within the spinocerebellar ataxia pathway were proteasome 26S subunit (PSMD1, PSMD7, PSMD12, PSMD13), specifically the non-ATPase regulatory components, which are central to the degradation of ubiquitinated proteins." (PMID 41441337, 2025).